BCL2 (BCL2 apoptosis regulator)
Diseases named in the same sentence as BCL2 in open-access papers (continued):
Sharing a sentence is not in itself a finding about the gene and the disease.
prostate carcinoma (continued). "Furthermore, Bcl-2 plays a critical role in promoting the transition from androgen-dependent to androgen-independent growth, a critical step in prostate cancer evolution, with its expression significantly upregulated in androgen-independent prostate cancer cells." (PMID 40841912, 2025). "Additionally, research on formononetin found that the export of Caspase-3, Bax, and Bcl-2 could be altered by this compound, which further led to the induction of apoptosis in lung and prostate cancers." (PMID 39338323, 2024). "Moreover, zinc reduces hypoxia-inducible factor-1α in prostate cancer cells and can have apoptotic effects by activating caspase-3 and caspase-9, and increasing levels of Bax protein, a pro-apoptotic protein; hence elevating the Bax/Bcl-2 ratio." (PMID 38507438, 2024). "In addition, clusterin appears to contribute to an anti-apoptotic environment in prostate cancer cells, potentially influencing Bcl-2 activity and leading to increased cell survival, although the direct activation of Bcl-2 by clusterin has not been fully established." (PMID 38535120, 2024). "Furthermore, it induced apoptosis in human prostate cancer cells PC-3 and DU-145 at higher concentrations (400–1000 μg/mL) through the regulation of the expression of Bcl2/Bax proteins, inhibiting proliferation and apoptosis of human cervical carcinoma (HeLa) cells via the mitochondrial pathway." (PMID 35684505, 2022). "Besides, overexpression of BCL-2 may promote the progression of prostate cancer by prolonging the net growth of tumors, thereby improving the survival rate of tumor cells." (PMID 36313628, 2022). "Therefore, our results in the study could potentially advance the clinical application of ZQD by showing that ZQD could treat prostate cancer through the miR-143/Bcl-2 axis." (PMID 34170852, 2021). "However, miR-143 dysregulation has not be associated with the androgen independence of prostate cancer, despite that the interaction between miR-143 and Bcl-2 has been implicated in other cancers." (PMID 34170852, 2021). "Moreover, in two individual prostate cancer studies 46, 47, we found that in patients with previous taxane treatment, higher levels of prostate specific antigen (greater than median) correlated with a higher level of BCL2 mRNA." (PMID 32685011, 2020). "Moreover, Bcl-2 upregulation is necessary for androgen-independent prostate cancer cell survival." (PMID 32344908, 2020). "Consequently, our data supported the role of the Eya2/AKT/Bcl-2 axis in prostate cancer cells." (PMID 31317026, 2019). "Similarly, hydroxytyrosol has previously increased the Bax/Bcl-2 ratio in prostate cancer cells." (PMID 30004416, 2018). "In prostate cancer, the role of BCL2 expression in disease progression is currently not fully understood: Stackhouse and coworkers reported a positive correlation between BCL2 tumor staining and biochemical recurrence in prostatectomy specimens, but not in prostate biopsies." (PMID 28396899, 2017). "In addition, BCL-2 identified in C4-2B might contribute to the progression of androgen-refractory prostate cancer." (PMID 26934861, 2016). "It has been reported that in prostate cancer NF-κB is overactivated, thus endocannabinoids may act through this pathway, simultaneously activating caspase-3, downregulating Bcl-2 expression; and other proteins that may also be involved in the apoptotic process." (PMID 25606819, 2015). "Only a few observational studies have investigated the relation of genetic variants in the BCL-2-gene family, particularly the BCL2 gene, with susceptibility to myeloid leukemia, squamous cell carcinoma of the head and neck, esophageal cancer and prostate cancer." (PMID 23637776, 2013). "In addition, overexpression of Bcl-2 can protect prostate cancer cells from apoptosis induced by MDA-7/IL-24, indicating that the caspase machinery activated by MDA-7/IL-24 in LNCaP cells might be preferentially inhibited only by Bcl-2." (PMID 22629368, 2012).
prostate carcinoma (continued). "Therefore, downregulation of bcl-2 could represent an important molecular mechanism by which AMP induces prostate cancer apoptosis." (PMID 22693649, 2012). "Thus, the accumulation of additional genomic aberrations may be ultimately responsible for tumor progression and poor prognosis of Bcl-2-positive prostate carcinomas." (PMID 20877598, 2010). "In prostate cancer cells, NFκB may promote cell growth and proliferation by regulating expression of genes such as c-myc, cyclin D1, and IL-6, and inhibit apoptosis through activation of expression of anti-apoptotic genes, such as Bcl-2 and Bcl-XL." (PMID 18226269, 2008). "Although Bcl-2 was shown to be related to decreased survival and malignant potential in urothelial transitional cell cancer, oesophagus cancer, prostate cancer and other cancers, we demonstrated here that Bcl-2 is an independent favourable prognostic factor in RCC patients." (PMID 14710230, 2004). "Neem-derived flavonoids and limonoids also inhibit STAT3, BCL-2, and enhance BAX, Caspase-3, and mitochondrial depolarization in hepatocellular and prostate cancers." (PMID 41346617, 2025). "EGCG showed promising results on prostate cancer stem cells through the inhibition of colony and spheres formation, the inhibition of EMT, the down-regulation of vimentin, Bcl-2, and survivin, and the up-regulation of caspase-3 and apoptosis induction." (PMID 39859345, 2025). "In this study, we aimed to determine the role of miR-143 in abiraterone acetate-resistant prostate cancer and its regulatory effects on the JNK/p-Bcl2-Beclin1 signaling axis." (PMID 41446858, 2025). "In this study, we investigated the role of miR-143 in abiraterone acetate-resistant prostate cancer and its regulatory effects on the p-JNK/p-Bcl2-Beclin1 signaling axis." (PMID 41446858, 2025). "In several lines of prostate cancer, including PC-3, LNCaP, and DU-145, it has been demonstrated that cryptophycin 52 is capable of activating the phosphorylation of BCL-xL and BCL-2." (PMID 40143065, 2025). "We initially assessed responses to navitoclax (targeting BCL-2/BCL-XL), venetoclax (targeting BCL-2), and S63845 (targeting MCL-1) in a series of prostate cancer PDX-derived primary cultures/3D spheroids, patient-derived organoids, and cell lines." (PMID 40436896, 2025). "Our analysis revealed that several maize miRNAs potentially target key regulators of prostate-cancer signaling, including PTEN, IGF1R, AR, FOXO1, GSK3B, and BCL2." (PMID 41440174, 2025). "The inhibition of the PI3K/AKT pathway, combined with the upregulation of the BAX/BCL2 ratio, collectively supports SSA’s pro-apoptotic and anti-tumor mechanisms, providing mechanistic evidence for its multi-targeted effects in prostate cancer treatment." (PMID 39995416, 2025). "It is reported that PARP1 is involved in DNA repair, and Bax/Bcl-2 is a pair of key genes for promoting/inhibiting apoptosis, while RB and PTEN mainly regulate one of the signals of the prostate cancer cell cycle, DNA damage response, and tumor suppression." (PMID 40649870, 2025). "Future research should focus on developing effective combination therapies that leverage Bcl-2 inhibition to overcome ARSI resistance and improve outcomes for patients with advanced prostate cancer." (PMID 40841912, 2025). "In order to better understand the role of apoptotic genes in prostate cancer, the STRING database was next used to characterize the interactions among NKX3‐1, caspase‐3, BCL‐2, caspase‐9, and a variety of other genes." (PMID 40344485, 2025). "Second, the induction of antiapoptotic signals by BMX are observed in different cancer types, including BCL2/BCL-xl expression in SCLC, and PIM-1 expression in prostate cancer." (PMID 39133652, 2024). "We observed a significant reduction in BCL-2 and CDK4 expression, along with an increase in Bax and PTEN, in prostate cancer cell lines upon MYC suppression." (PMID 38756697, 2024).
prostate carcinoma (continued). "In prostate cancer cells (PC-3), radiation-induced TNF-α increased NF-κB activity, resulting in the induction of Bcl-2 protein." (PMID 39519572, 2024). "We found that EXO1 promoted BCL2, CDC25, and PCNA and inhibited BAX expression, and further experiments showed that EXO1 inhibited apoptosis in prostate cancer cells." (PMID 38279172, 2024). "Several anti-apoptotic members of the bcl-2 gene family, including BCL2, BCL-X, and MCL-1 showed high expression during the progression of prostate cancers." (PMID 38195593, 2024). "It was observed that the introduction of miR-377 resulted in a notable decrease in the presence of BCL-2 mRNA in both PC-3 and DU145 prostate cancer cells." (PMID 38756697, 2024). "Treatment of the androgen-dependent prostate cancer cell line LNCaP with saffron induced decreased expression of CD44 and Bcl-2; these are hallmarks of apoptosis, which clearly supports saffron’s anti-tumor function via apoptosis." (PMID 38201944, 2023). "EA also increases the expression of Bcl-2 inhibitory proapoptotic proteins PUMA and Noxa in prostate cancer cells." (PMID 38002335, 2023). "Several published papers have found that NF-κB binds to the promoters of BCL2, BCL2A1, and MCL1 and activates their expression in many cell types, such as prostate cancer cells, esophageal squamous carcinoma cells, and fibrosarcoma cells." (PMID 36853387, 2023). "We now verified the cooperative protection from apoptosis by Bcl-2, Bcl-xL, and Mcl-1 in LNCaP and PC3 prostate cancer cells." (PMID 37173959, 2023). "Zhou and co-workers have reported that vitexin showed a cytotoxic effect on breast, ovarian, and prostate cancer cells by inducing apoptosis with the cleavage of the PARP protein, the upregulation of Bax and downregulation of Bcl-2." (PMID 36826044, 2023). "Seven genes (ATM, BCL2, ERN1, FOS, NRAS, PIK3R1, and SP1) were regulated in opposite directions in patients with HD and prostate cancer." (PMID 37298337, 2023). "Some studies have shown that CXCL3 promotes prostate cancer cell proliferation and migration by upregulating p-ERK1/2, p-Akt, and Bcl2 and downregulating Bax." (PMID 37445610, 2023). "Mechanistic studies showed that Co-Sp reduced the expression of cyclin D1, cyclin E, CDK4, CDK2, MMP-9, MMP-1, and Bcl-2, and increased the expression of p21, cleaved caspase-9, cleaved caspase-3, cleaved PARP, and Bax in prostate cancer cells." (PMID 37313467, 2023). "Previous studies in prostate cancer have also shown that miR-143-3p can inhibit cell growth through various targets, including KRAS, Bcl-2, ERK5, LIMK1, HK2 and KLK2." (PMID 37759434, 2023). "The combination therapy of nanocarriers significantly decreased expression of the Bcl-2 gene and promoted the cell death of PC3 cells, providing an applicable drug delivery approach against prostate cancer." (PMID 36874010, 2023). "In the case of prostate cancer, apigenin decreased Bcl-2 and Bcl-xL and increased BAX in PC-3 and DU145 human prostate cancer cells." (PMID 36142874, 2022). "Finally, a molecular docking was attempted to investigate the binding mode of the identified compounds in Bcl-2 proteins’ receptor, implying that the fruits and their nanoparticles are excellent candidates for treating skin infections in patients with ovarian or prostatic cancer." (PMID 36355526, 2022). "In this regard, the present work aimed to fabricate bismuth oxide nanoparticle functionalized with glutamine and conjugated with TSC and to characterize its effect on prostate cancer cells and expression of CASP8, BAX, and Bcl-2 genes." (PMID 36482061, 2022).
prostate carcinoma (continued). "In the current study, solasonine treatment significantly suppressed Bcl‐2 protein expression in SGC‐7901 cells, which was consistent with previous findings in HCC HepG2 cells and prostate cancer PC‐3 cells." (PMID 35524577, 2022). "of prostate cancer metastases showed that prostate cancer bone metastases had increased expression of MCL-1 (myeloid leukemia 1) and BCL-2 (B-cell lymphoma 2), key contributors in cell survival, compared to other sites of metastases." (PMID 36466910, 2022). "Infection with Ad.5-CTV or Ad.5-TCTV caused comparable changes in pro- and anti-apoptotic proteins, i.e., decreased BCL-2 and increased PARP expression, in breast and prostate cancer cells." (PMID 33670594, 2021). "Since Bcl-2 is a target of miR-143, ZQD therapy downregulates Bcl-2 and upregulates Caspase-3 and Bax2 to suppress prostate cancer progression." (PMID 34170852, 2021). "Prostate cancer patient data from two datasets was used to identify the roles of TGF-β, Bcl-2 and KLF5 in prostate cancer." (PMID 32685011, 2020). "Preclinical studies have shown that the Bcl-2 promoter has ARE binding sites and that ligand activation of AR in prostate cancer cell lines directly represses Bcl-2 transcription and COX2 expression via modulation of NF-κB signaling." (PMID 32850312, 2020). "A recent study found upregulation of BCL2 and WEE1 kinase in small cell neuroendocrine (SCN) cancers, and combining Navitoclax and the WEE1 inhibitor AZ-1775 was synergistic against SCN prostate cancer patient-derived xenografts." (PMID 32572160, 2020). "The levels of procaspase-3, -8, and -9, as well as Bid and Bcl-2, decreased, while the levels of cleaved-PARP and Bax increased following sanggenol L treatment of prostate cancer RC-58T cells." (PMID 32075054, 2020). "Next, we assess the ability of a small molecule Bcl-2 specific inhibitor, ABT-199, to sensitize prostate cancer cells to DTX treatment." (PMID 32685011, 2020). "A decreased BCL2/BAX ratio, together with increased caspase-3 activity and protein abundance were observed in PC-3, DU-145 and LNCaP prostate cancer cells after using CAPE synergistically with docetaxel and paclitaxel." (PMID 32752091, 2020). "In this study, we showed that the levels of procaspases-3, -8, and -9, Bid, and Bcl-2 decreased and the levels of cleaved-PARP and Bax increased in prostate cancer RC-58T cells following sanggenol L treatment." (PMID 32075054, 2020). "The POU1F1-derived tumors have 499 exclusive proteins that participate in events such as Platinum drug resistance (AKT3, BCL2 and GSTT2) and Prostate cancer (FGFR1, IGF1R and PDGFD) among others." (PMID 33261069, 2020). "Arctigenin, an active lignin constituent of this plant, exerts an anti-inflammatory property and has the potency to cure prostate cancer by downregulating the expression of VEGF, EGF, and bFGF, as well as upregulating the expression of Bax/Bcl-2." (PMID 30871059, 2019). "Collectively, our current data revealed that EYA2 promoted the progression of prostate cancer, potentially via the AKT/Bcl-2 axis." (PMID 31317026, 2019). "EGCG, the major catechin from green tea, reduced the level of Bcl-2, increased the level of Bax, and induced the activation of caspase-3, -8, -9, and PARP in a dose- and time-dependent manner in androgen-positive prostate cancer cells." (PMID 30823649, 2019). "In human prostate cancer LNCaP cells, NO upregulates RUNX2 and Bcl2 expression which confers resistance to chemotherapy." (PMID 30972102, 2019).
prostate carcinoma (continued). "Similar results were observed in LNCaP prostate cancer cells, and AL treatment dose-dependently increased the ratio of BAX and Bcl-2." (PMID 31467577, 2019). "Another study provided direct evidence that NFκB transcriptionally regulates bcl2 gene expression, directly linking the TNF-α/NFκB signaling pathway to bcl2 expression in human prostate carcinoma cells." (PMID 29497611, 2018). "Compound 7 showed selectivity for Bcl-xL (KD = 6.5 μM) over Bcl-2 (KD = 160 μM) protein, and potent cytotoxicity (nanomolar scale) in PC-3, PC-3a and DU145 prostate cancer cells." (PMID 28881653, 2017). "The miR-135a reduces the invasion and metastasis of prostate cancer by inhibiting ROCK123 and induces the apoptosis of various cells by inhibiting HOXA10 and BCL-2 expression." (PMID 28729631, 2017). "These miRNAs target several oncogenes such as BCL2, Cycline D1 (CCND1) and WNT3A in prostate cancer." (PMID 28783103, 2017). "All the selected genes show a strong relation with the disease, such as FGFR2 and BCL2, which were selected by both Net-Cox and fastcox and are involved in KEGG prostate cancer and in KEGG pathways in cancer." (PMID 27378931, 2016). "Up-regulated BCL2, CCND1 and WNT3A which promote tumorigenic features, are the main targets of miR-15a and miR-16-1 in prostate cancer." (PMID 25743273, 2015). "Over-expression of Bcl-2 inhibits ceramide-induced JNK activation, indicating that Bcl-2 is upstream of ceramide-induced JNK pathway in prostate carcinoma cells." (PMID 25751724, 2015). "Tumors with CAM2KN1 knockdown have reduced expression of p21, Bax and increased AR, pAKTser473, PSA, Bcl-2 and Ki67 expression, suggesting that reduction of CAM2KN1 promotes growth in AR positive prostate cancer cells." (PMID 25296973, 2014). "Rapid activation of caspase-3 along with down-regulation of Bcl-2 and up-regulation of Bax in the presence of 0.1 mg/ml amygdalin has been demonstrated in DU145 and LNCaP prostate cancer cells." (PMID 25136960, 2014). "Tumors overexpressing CAM2KN1 have reduced expression of Bcl-2, Ki67 and increased p21 and Bax expression, suggesting that gain of CAM2KN1 promotes apoptosis in prostate cancer cells." (PMID 25003983, 2014). "In human prostate cancer, SAC can elevate apoptosis of the cancer cells under in vivo environment through activation of cleaved caspase-3 and down-regulation of Bcl-2." (PMID 22389672, 2012). "In accord, melatonin has been shown to reduce both survivin and Bcl-2 protein levels and subsequently increase the sensitivity of human PC3 prostate cancer cells to TNF-α." (PMID 20920299, 2010). "Functionally, WT1 has been shown to regulate genes important in prostate cancer including VEGF, Bcl2, AR, and IGF1R." (PMID 20426842, 2010). "Some of these genes have known functions in prostate cancer, such as FGFR1, BCL2, HOXC5, HOXA4, TWIST1, EZH2, KLF4, CTGF." (PMID 19262738, 2009).